ARMH4 (armadillo like helical domain containing 4)
Description:
May modulate immune response and may play a role in inflammation. Down-modulates STAT3 signaling throught direct interaction with IL6ST, resulting in the inhibition of phosphorylation of STAT3 at 'Tyr-705'. May negatively regulates AKT signaling by modulating the activity of mTORC2 complex through RICTOR interaction (By similarity).
Synonyms: C14orf37; UT2; c14_5376
Tractability: Antibody: UniProt predicts a signal peptide or a membrane-spanning region; the Human Protein Atlas places it where antibodies can reach.
Gene: Protein-coding gene on chromosome 14 (57,999,735 to 58,298,139, reverse strand). Ensembl gene ENSG00000139971.
Subcellular location: Membrane
Subcellular location (Human Protein Atlas): Plasma membrane
Gene Ontology:
Molecular function: protein binding; TORC2 complex binding
Biological process: regulation of inflammatory response; regulation of TORC2 signaling
Cellular component: membrane
Genetic constraint (gnomAD): Loss-of-function variants: 45 observed, 60.51 expected, observed/expected ratio (o/e) 0.74, 90% interval 0.58 to 0.95. The upper end of that interval is the gene's LOEUF score, 0.95, which puts it in group 4 of 6, group 1 being the genes least tolerant of losing a copy. Missense variants: 923 observed, 969.9 expected, observed/expected ratio (o/e) 0.95, 90% interval 0.9 to 1. Synonymous variants: 368 observed, 358.9 expected, observed/expected ratio (o/e) 1.03, 90% interval 0.94 to 1.12.
Homologues: Orthologues: chimpanzee ARMH4 (98% identical), macaque ARMH4 (93% identical), dog ARMH4 (75% identical), pig ARMH4 (70% identical), rabbit ARMH4 (68% identical), rat Armh4 (57% identical), mouse Armh4 (56% identical), tropical clawed frog ARMH4 (30% identical).
Diseases named in the same sentence as ARMH4 in open-access papers:
ARMH4 is named in the same sentence as 12 diseases in open-access papers, as found by Europe PMC text mining. Sharing a sentence is not in itself a finding about the gene and the disease. The quoted sentences say what the papers report.
crescentic glomerulonephritis (1 paper, 2023). A histopathologic term for a pattern of diseases characterized by extensive crescent formation in the glomeruli; patients present clinically with rapid deterioration of renal function, and possible progression to end-stage renal failure within weeks or months. "In crescentic glomerulonephritis, in particular, ARMH4 seemed to be normally expressed in the smaller healthy segment of a glomerulus, while it was absent in a fibrotic area of the same glomerulus." (PMID 36649229, 2023).
focal segmental glomerulosclerosis (1 paper, 2023). A renal disorder characterized by sclerotic lesions in the glomeruli. "Using available RNA-seq data from human glomeruli, ARMH4 was found to be downregulated in glomerular diseases such as collapsing and classic focal segmental glomerulosclerosis (FSGS) compared to normal tissue." (PMID 36649229, 2023). "Glomerular gene profiles available in NephroSeq, revealed that both ARMH4 (C14orf37) and WIPF3 were reduced in diseased kidneys, with the largest difference seen for ARMH4 in collapsing and classic focal segmental glomerulosclerosis (Coll." (PMID 36649229, 2023).
lupus nephritis (1 paper, 2023). Glomerulonephritis in the context of systemic lupus erythematosus. "Such an immune modulatory and anti-inflammatory effect of this protein is of clear interest given the previously reported association between a variant at the ARMH4 locus and lupus nephritis." (PMID 36649229, 2023). "This approach identified several human podocyte markers, including ARMH4 and WIPF3, which were previously identified in genome-wide association studies for lupus nephritis and albuminuria, respectively." (PMID 36649229, 2023). "Two of the markers identified in our analyses, MYL3 and WIPF3, were GWAS hits for albuminuria, and one, ARMH4, was a hit for lupus nephritis." (PMID 36649229, 2023).
membranous nephropathy (1 paper, 2023). "In line with this, our independent immunohistochemistry on biopsies from patients suffering from minimal change disease, FSGS, membranous nephropathy, and pauci-immune crescentic nephritis showed an apparent downregulation of ARMH4 immunoreactivity." (PMID 36649229, 2023).
tumor (3 papers, 2021 to 2023). "A recent publication based on the application of multivariate regression algorithms suitable for higher dimension data identified 3 genes (MAMDC2, SYNPO2 and ARMH4) as biomarkers of gene expression signatures for tumor and marginal tissue zones." (PMID 38188288, 2023). "ARMH4 (C14orf37, UT2) has been implicated as a tumour suppressor in myeloma and was found here downregulated in margins relative to the normal tissue." (PMID 35327656, 2022). "It has been shown that ARMH4 can interact with and inhibit the function of mTOR complex 2 kinase activity and function as a tumor suppressor in hematological malignancies, which is driven by interleukin 6 (IL-6)–signal transducer and activator of transcription 3 (STAT3) signaling pathways." (PMID 34660292, 2021).
cancer (2 papers, 2021 to 2022). A tumor composed of atypical neoplastic, often pleomorphic cells that invade other tissues. "Armh4 is a type-Itransmembrane protein implicated in regulating cell proliferation in the contextof stem cells and cancer but has nodescribed roles in the nervous system." (PMID 36220098, 2022).
kidney diseases (1 paper, 2023). "Given the anti-inflammatory impact of ARMH4, we speculate that its apparent reduction in kidney diseases may contribute to inflammation in glomerulonephritides." (PMID 36649229, 2023).
ARMH4 also shares sentences with these, for which no sentence is quoted: co-infection (1 paper); glomerular diseases (1); hematological malignancies (1); kidney cancer (1); minimal change disease (1).